ACSL1 (acyl-CoA synthetase long chain family member 1)
Diseases named in the same sentence as ACSL1 in open-access papers (continued):
Sharing a sentence is not in itself a finding about the gene and the disease.
Alzheimer disease (4 papers, 2024 to 2026). A progressive, neurodegenerative disease characterized by loss of function and death of nerve cells in several areas of the brain leading to loss of cognitive function such as memory and language. "In human induced pluripotent stem cell-derived microglia, Aβ induces acyl-CoA synthetase long-chain family member 1 expression, triglyceride synthesis and lipid droplet accumulation in Alzheimer’s disease (AD) having the APOE4/4 genotype." (PMID 39809738, 2025).
dyslipidemia (4 papers, 2012 to 2019). "An association between ACSL1 gene polymorphisms and the metabolic syndrome has recently been reported." (PMID 23028366, 2012). "LIPGENE-SU.VI.MAX study shows that not only mutation in glucose metabolism but also in fatty acid metabolism cause IR and dyslipidemia, as evidenced by mutations in long-chain acyl CoA synthetase 1 (ACSL1) gene that is an important enzyme for mitochondrial beta-oxidation of long chain fatty acids." (PMID 27894098, 2017). "Here, ACSL1 gene expression was lower in individuals with metabolic syndrome." (PMID 23028366, 2012). "Exploiting the differences among the ACSLs may allow the targeting of specific acyl-CoA synthetases, such as ACSL1, with small-molecule inhibitors and thus open new therapeutic avenues against lipotoxicity in clinical contexts such as dyslipidemia or liver steatosis." (PMID 31769755, 2019).
glioma (4 papers, 2022 to 2024). A benign or malignant brain and spinal cord tumor that arises from glial cells (astrocytes, oligodendrocytes, ependymal cells). "Low ACSL1 expression is associated with a better prognosis in patients with IDH1-mutant glioma." (PMID 39524444, 2024). "Several studies revealed expression of ACSL1 is related to the progression and prognosis of glioma and amyotrophic lateral sclerosis (ALS)." (PMID 36507355, 2022). "A previous analysis based on The Cancer Genome Atlas (TCGA) RNA sequencing data suggested lower expression of ACSL1 influences metabolic reprogramming and contributes to the better survival of patients with isocitrate dehydrogenase 1 (IDH1) mutant glioma." (PMID 36507355, 2022). "Despite their potential as targets in gliomas, no preclinical studies have developed inhibitors to selectively target ACSL1 or ACSL5." (PMID 36012521, 2022).
Hyperglycemia (4 papers, 2019 to 2023). An increased concentration of glucose in the blood. "This study shows a strong association of Acsl1 expression with CHREBP in hyperglycemia and NF-kappa B under inflammatory conditions." (PMID 36054206, 2022). "BeWo cytotrophoblasts exposed to hyperglycemia displayed increased mRNA expression of ACSL1, HSD11B2, RPS6KA5, and LAP3 and reduced mRNA expression of CYP2F1, and HK2, concomitant with increased levels of: lactate, malonate, and riboflavin metabolites." (PMID 36930661, 2023). "Human ACSL1 is transcriptionally regulated by NF-κB and carbohydrate response element binding protein in macrophages during hyperglycemia and inflammation." (PMID 37509093, 2023). "Thus, CHREBP and p65/RELA occupy the Acsl1 promoter in BMDMs under conditions of hyperglycemia and inflammation." (PMID 36054206, 2022). "In addition to hyperglycemia, Acsl1 expression in macrophages is induced by inflammatory stimuli, such as lipopolysaccharide (LPS) and gram-negative bacteria (E. coli)." (PMID 36054206, 2022). "The expression of Acsl1 mRNA is induced by inflammation and hyperglycemia." (PMID 36054206, 2022). "Thus, hyperglycemia induces the transcription of the Acsl1 gene in BMDMs." (PMID 36054206, 2022). "Therefore, we hypothesized that CHREBP upregulates Acsl1 expression in macrophages in response to hyperglycemia." (PMID 36054206, 2022). "Regardless, our studies reveal that hyperglycemia and inflammation and their related transcription factors CHREBP and NF-kappa B foster Acsl1 expression in macrophages to support the production of acyl-CoA derivatives." (PMID 36054206, 2022). "However, the mechanism whereby Acsl1 is upregulated by hyperglycemia is not understood." (PMID 36054206, 2022).
lipid metabolism disorder (4 papers, 2021 to 2025). "RXRA, a member of the RXR family that can be activated by sterol, modulates the lipid metabolism disorders by activating acyl-CoA synthetase long-chain family member 1 (ACSL1)." (PMID 34421622, 2021). "Specifically, LLPK intervenes in biological processes such as lipogenesis, fatty acid oxidation, and fatty acid transport in mice livers by regulating the expression of key downstream factors of PPARα (Scd1, Acox1, Acaa1b, Slc27a1, Acsl1, and Ehhadh), thus improving lipid metabolic disorders." (PMID 40431433, 2025). "These DEGs included ACSL1, ANGPTL3, and ELOVL6, suggesting the possibility of a lipid metabolism disorder in the liver of exposed T. scripta elegans." (PMID 39088466, 2024).
liver fibrosis (4 papers, 2016 to 2024). "In general, our findings revealed that miR-34c plays an essential role in liver fibrosis by targeting ACSL1 closely associated with lipid, and it might be used as a potential therapeutic target." (PMID 33437196, 2021). "Our results indicate that miR-34c plays an essential role in liver fibrosis by targeting ACSL1 closely associated with lipid droplets, and it might be used as a potential therapeutic target." (PMID 33437196, 2021). "As a crucial target of miR-34c, ACSL1 (acyl-CoA synthetase long-chain family member 1) is involved in HSCs activation during liver fibrosis." (PMID 39195573, 2024). "Inhibition of miR-34c can restore ACSL1 levels and potentially improve liver fibrosis by restoring lipid metabolism and maintaining HSCs quiescence." (PMID 39195573, 2024). "Transfection of miR-34a silencing vector using Lipofectamine2000 into activated HSCs increased the expression of ACSL1 and promoted lipogenesis, thereby inhibiting HSCs activation and hepatic fibrosis." (PMID 35795649, 2022). "MiR-34c inhibition partly restored the function of ACSL1, further validating that miR-34c and promoting initiation and development of liver fibrosis by targeting ACSL1." (PMID 33437196, 2021). "This is the first research showing miR-34c to have a regulatory effect on HSC activation and promotes hepatic fibrosis by targeting ACSL1, a key enzyme related to fatty acid and lipid synthesis closely." (PMID 33437196, 2021). "In summary, using functional experiments with HSC and in vivo experiments in rats, we further confirmed that miR-34c promotes development of hepatic fibrosis by targeting ACSL1." (PMID 33437196, 2021). "Our research has shown that miR-34c activates and proliferates HSC to further promote liver fibrosis by targeting ACSL1." (PMID 33437196, 2021). "Therefore, it is necessary to further study the regulation of ACSL1 to lipid and the role of lipid in the development of hepatic fibrosis, it is of utmost interest to find new breakthroughs in the mechanisms of liver fibrogenesis and its reversal." (PMID 33437196, 2021). "Thus, ACSL1 is one of the factors by which miR-34a promotes hepatic fibrosis." (PMID 35795649, 2022). "The expression of ACSL1 at the protein level increased 1.49-fold, whereas the expression of α-SMA and Col1α in liver fibrosis decreased by 18.22% and 2.58%, respectively." (PMID 33437196, 2021).
type 1 diabetes (4 papers, 2019 to 2025). "ACSL1/Acsl1 is also induced in monocytes from humans and mice with type 1 diabetes, and its deficiency in myeloid-specific Acsl1-deficient mice leads to decreased expression of proinflammatory cytokines, including IL-1β and TNF." (PMID 30914513, 2019). "Small human cohorts also hint at myeloid cell ACSL1 expression being elevated in peripheral blood mononuclear cells (PBMCs) or whole blood in inflammatory states, such as type 1 diabetes or following a myocardial infarction or ischemic stroke." (PMID 39675509, 2025). "In the immune system, upregulated ACSL1 expression promoted the inflammatory phenotype of macrophages isolated from mouse models of type 1 diabetes." (PMID 34960652, 2021).
clear cell renal cell carcinoma (3 papers, 2019 to 2025). "In this study, we investigated the immunohistochemical expression of CD36, FATP4, and ACSL1 in 180 cases of clear cell renal cell carcinoma (RCC) in comparison with 80 specimens of the normal kidney." (PMID 31089396, 2019).
Granuloma (3 papers, 2012 to 2022). A compact, organized collection of mature mononuclear phagocytes, which may be but is not necessarily accompanied by accessory features such as necrosis. "Nascent TB granulomas showed little-to-no presence of these three proteins, resolved/calcified TB granulomas showed none, and caseous and fibrocaseous TB granulomas demonstrated abundant ADFP, ACSL1 and SapC." (PMID 35386409, 2022).
non-small cell lung carcinoma (3 papers, 2019 to 2024). A group of at least three distinct histological types of lung cancer, including non-small cell squamous cell carcinoma, adenocarcinoma, and large cell carcinoma. "Moreover, in vitro experiments show that RNA interference-mediated ACSL1 knockdown enhances the proliferation and invasiveness of non-small cell lung cancer cell lines." (PMID 31344914, 2019). "ACSL1 is reported to be downregulated in non-small cell lung cancer." (PMID 31344914, 2019).
thyroid cancer (3 papers, 2023 to 2024). "Existing studies shown that upregulation of ACSL1 is regulated by SNHG7/ miR-449a to cause proliferation and migration of thyroid cancer cells." (PMID 37596597, 2023). "The high expression of acyl-CoA synthetase long-chain family member 1 (ACSL1) inhibits the progression of thyroid cancer cells and activates fatty acid metabolism reprogramming during cancer cell metastasis, thereby achieving an antagonizing effect of ferroptosis on tumour cells." (PMID 36600313, 2023).
acute myeloid leukemia (2 papers, 2024 to 2025). Acute myeloid leukemia (AML) is a group of neoplasms arising from precursor cells committed to the myeloid cell-line differentiation. "Conversely, up-regulation of ACSL1 expression can promote sensitivity to ferroptosis in acute myeloid leukemia." (PMID 40042449, 2025). "Protein arginine methyltransferase 1 (PRMT1) can promote histone methylation in the promoter region of ACSL1, thus decreasing the level of lipid peroxidation and mediating ferroptosis resistance in acute myeloid leukemia (AML)." (PMID 38459004, 2024).
amyotrophic lateral sclerosis (2 papers, 2022 to 2024). Amyotrophic lateral sclerosis (ALS) is a neurodegenerative disease characterized by progressive muscular paralysis reflecting degeneration of motor neurons in the primary motor cortex, corticospinal tracts, brainstem and spinal cord. "A more comprehensive analysis indicates that upregulated proteins (ELOVL5, ELOVL7, TECR, HSD17B4, ACSL1, HACD2, and CBR4) are significantly enriched within the pathways of oxidative phosphorylation and metabolic pathways pertinent to amyotrophic lateral sclerosis." (PMID 39335340, 2024).
bladder cancer (2 papers, 2021 to 2025). "Although FATP4, CD36, and ACSL1 showed weak positive correlation among them in this study, it is uncertain if FATP4, CD36 or ACSL1 might interact with each other and have a synergistic effect on the transport of fatty acids in bladder cancer cells." (PMID 34257543, 2021). "ACSL1 was exclusively localized to the cytoplasm of bladder cancer cells." (PMID 34257543, 2021). "The protein expression and prognostic value of FATP4 and ACSL1 have never been studied in human bladder cancers." (PMID 34257543, 2021). "However, the prognostic value of ACSL1 has been differently described according to the cancer type and its protein expression in bladder cancer has never been studied." (PMID 34257543, 2021). "High CD36 and ACSL1 failed to predict overall survival of bladder cancer patients." (PMID 34257543, 2021). "Although CD36 and ACSL1 failed to predict OS and RFS in this NMIBC cohort, it could be assumed that CD36 and ACSL1 might have roles in the progression of bladder cancers and could be targetable along with FATP4." (PMID 34257543, 2021).
Cachexia (2 papers, 2020 to 2025). Severe weight loss, wasting of muscle, loss of appetite, and general debility related to a chronic disease. "Altered hepatic mitochondrial function with suppressed ACSL1 appeared associated with cachexia severity." (PMID 33266387, 2020). "Another recent study revealed altered mitochondrial metabolism and suppressed acyl-CoA synthase-1 (ACSL1) in mice with colon-26-induced cachexia." (PMID 33266387, 2020). "This raises the intriguing question of whether ACSL1 could serve as a potential therapeutic target in cachexia." (PMID 41288931, 2025). "Notably, deletion of ACSL1 has been observed in cachexia, a phenomenon that has not been previously reported." (PMID 41288931, 2025).
cardiac hypertrophy (2 papers, 2012 to 2024). "Mice lacking ACSL1 specifically in adipose tissue have defects in adipose FFA oxidation, whereas those unable to express ACSL1 in heart ventricles show compensatory catabolism of glucose and amino acids leading to mTOR activation and cardiac hypertrophy without lipid accumulation or dysfunction." (PMID 22829935, 2012).
cervical cancer (2 papers, 2022 to 2023). A primary or metastatic malignant neoplasm involving the cervix. "By reviewing previous references, it was found that ACSL1 was an unexplored gene in cervical cancer." (PMID 36408176, 2022).
chronic myeloid leukemia (2 papers, 2022 to 2025). "Here, we found that a higher ACSL1 level exists in senescent K562 cells and increased ACSL1 promotes imatinib-induced chronic myeloid leukemia cell senescence." (PMID 36289272, 2022).
colitis (2 papers, 2022 to 2024). Inflammation of the colon. "Our data showed that the enzymes ACSL1 and ACADM, which break down long-chain fatty acids and medium-chain fatty acids, respectively, were significantly decreased in colitis." (PMID 38668322, 2024). "We also examined SGK1, CEP55, ACSL1, OLFM4, DPP10, and MGP expression in the colon tissues of dextran sodium sulfate‐induced colitis mice." (PMID 34939750, 2022). "To further confirm the differential expression of these candidate genes between ulcerative colitis and normal groups, we determined the mRNA expression of SGK1, CEP55, ACSL1, OLFM4, MGP, and DPP10 in colon tissues of DSS‐induced colitis mice." (PMID 34939750, 2022). "In addition, we also examined the expression of SGK1, CEP55, ACSL1, OLFM4, DPP10, and MGP in the colon tissues of DSS‐induced colitis mice." (PMID 34939750, 2022). "In addition, we also examined the expression of SGK1, CEP55, ACSL1, OLFM4, DPP10, and MGP in the colon tissues of dextran sulfate sodium‐induced colitis mice." (PMID 34939750, 2022).
diabetic kidney disease (2 papers, 2023 to 2025). Progressive kidney disorder caused by vascular damage to the glomerular capillaries, in patients with diabetes mellitus. "Conversely, reduced expression of protein arginine methyltransferase 6 (PRMT6) expression promotes lipid peroxidation and PL-PUFA synthesis by upregulating ACSL1, thereby exacerbating ferroptosis and accelerating diabetic nephropathy progression." (PMID 41288931, 2025).
hyperlipidemia (2 papers, 2022 to 2025). "Liver Acsl1 deficiency induced severely hepatic triglyceride accumulation and hypercholesterolemia, particularly accompanied with hyperlipidemia." (PMID 36235710, 2022). "Long‐chain fatty acyl‐CoA synthetase 1 (ACSL1) is upregulated in both hyperlipidemia and AMI patients." (PMID 39853712, 2025). "This phenomenon was also observed in patient samples, establishing ACSL1 as a crucial player in the pathogenesis of hyperlipidemia and AMI." (PMID 39853712, 2025). "Finally, our study pinpointed LPC and LPA as key downstream metabolites and established the ACSL1‐LPC‐ATX‐LPA axis as an intricate metabolic pathway that aggravates thromboinflammation in AMI due to hyperlipidemia." (PMID 39853712, 2025). "In summary, hyperlipidemia accelerates thromboinflammation in vitro and in vivo via ACSL1‐dependent monocyte activation, further demonstrating that NETosis is accelerated in hyperlipidemic states, which consequently aggravates the thromboinflammatory process in mIRI." (PMID 39853712, 2025). "The cardiac marker cardiac troponin (Tn) was also increased in hyperlipidemia and AMI patients, with a significantly positive relationship between ACSL1 levels and cardiac markers in patients." (PMID 39853712, 2025). "Notably, metabolic DEGs such as ACSL1, ABCA1, ABCG1, ACAT2, ALOX5AP, PLA1A, and PPARG were elevated in hyperlipidemia." (PMID 39853712, 2025).
liver disease (2 papers, 2025). "Hepatocyte fatty acid accumulation occurs in the absence of PPARα in the liver, leading to reduced levels of proteins and enzyme genes involved in fatty acid metabolism (such as ACSL1), thereby initiating and progressing liver disease." (PMID 39947476, 2025). "Moreover, Lira significantly upregulated ferroptosis-related proteins, including ACSL1, GCLM, and GCLC, indicating enhanced glutathione production, which protects cells from ferroptosis, a lipid peroxidation-related cell death process associated with liver disease." (PMID 41377138, 2025).
Multiple Myeloma (2 papers, 2014 to 2025). "Analysis of the Multiple Myeloma Research Foundation (MMRF) CoMMpassSM study showed that high ACSL1 and ACSL4 expression in myeloma cells are both associated with worse clinical outcomes for MM patients." (PMID 39853696, 2025).
myeloma (2 papers, 2014 to 2025). "Chromosomal segments containing genes such as LYST, CLK1, ACSL1 and NFKB1A were amplified in more than 40% of myeloma patients in this study." (PMID 24690091, 2014). "ACSL1, ACSL3, ACSL4, and ACSL5 are expressed in primary myeloma cells and supportive of myeloma cell fitness, suggesting that broad targeting of the ACSLs could be impactful for MM patients." (PMID 39853696, 2025).
myocardial ischemia (2 papers, 2025). A disorder of cardiac function caused by insufficient blood flow to the muscle tissue of the heart. "This research emphasized the role of ACSL1 in linking hyperlipidaemia to myocardial ischemia–reperfusion injury, particularly through phospholipids like LPC(16:1)." (PMID 40176064, 2025).
Neonatal sepsis (2 papers, 2022 to 2023). Systemic inflammatory response to infection in newborn babies. "For example, ACSL1, which is involved in shuttling fatty acids to mitochondria for β-oxidation and lipid synthesis pathways, is upregulated in human neonatal sepsis." (PMID 37919720, 2023).
Non-alcoholic fatty liver disease (2 papers, 2019 to 2020). "These proteins were mainly involved in fatty acid metabolism (Fasn, Scd1, Fads2, Fdps, Plin2), fatty acid degradation (Ehhadh, Acsl1), PPAR signaling pathway (Fads2, Ehhadh, Acsl1, Fabp1), non-alcoholic fatty liver disease (Ehhadh, Pklr) and AMPK signaling pathway (Fasn, Scd1, Hnf4a)." (PMID 32210812, 2020).